ANTXR1 (ANTXR cell adhesion molecule 1)
Diseases named in the same sentence as ANTXR1 in open-access papers (continued):
Sharing a sentence is not in itself a finding about the gene and the disease.
cancer (continued). "Further studies will address the impact of the ANTXR1 expression at the protein level, as it could give more information or the role in cancer cells vs. somatic cells." (PMID 39917181, 2024). "Further studies will explore the role of the isoform in cancer metabolism, as well as the impact that these might have in the downstream pathways from ANTXR1." (PMID 39917181, 2024). "Moreover, the upregulation of ANTXR1 in tumors makes SVA a convenient therapeutic treatment for the targeted killing of cancer cells." (PMID 35322150, 2022). "We anticipate our findings will aid in selecting patients for future cancer therapeutics, where screening for both ANTXR1 and its glycosylation could lead to an improved outcome from SVV therapy." (PMID 33924774, 2021). "Therefore, the function of Antxr1 in the proliferation of endothelial cells differs between physiological conditions and cancer angiogenesis." (PMID 32244499, 2020). "Interestingly, among the most significantly enriched KEGG pathway gene sets, two groups of cancer-associated gene sets including focal adhesion and TGF-beta signaling pathway were highly enriched in patients harboring high ANTXR1 expression level." (PMID 33385012, 2020). "Additionally, we found that ANTXR1 can induce T cell exhaustion, which can lead to poor clinical outcomes and failure of immunotherapy of cancer." (PMID 33385012, 2020). "Thus, Antxr1 positively regulates the proliferation of both endothelial cells in cancer and the cancer cells themselves but negatively regulates endothelial cell proliferation in physiological conditions." (PMID 32244499, 2020). "The remaining nine surface proteins identified solely (ANTXR1, AG1, DCBLD2, EFNB1, EMB, OSMR, SLC1A5) or found upregulated (ATP1B3 and ITGB1) on the MCF10A surface had no direct association with embryonic development signaling in the context of KRas mutant signaling in cancer cell lines." (PMID 27894102, 2016). "SVV specifically identifies and kills cancer cells by recognizing Tumor endothelial marker 8 (TEM8), also known as Anthrax toxin receptor 1 (ANTXR1), a cell surface receptor highly expressed in cancer cells." (PMID 40833065, 2025). "Enriched in several cancer types, TEM8/ANTXR1 is an integrin-like, transmembrane glycoprotein adhesion molecule that meditates cell movement and its interactions with the extracellular matrix (ECM)." (PMID 36851761, 2023). "Tumor endothelial marker 8 (TEM8), also known as anthrax toxin receptor 1 (ANTXR1), is highly expressed in cancers." (PMID 36769365, 2023). "Tumor endothelial marker 8 (TEM8), also known as ANTXR1, was highly expressed in cancers, and was identified as a biomarker for early diagnosis and prognosis in some cancers." (PMID 34722259, 2021). "Gene set enrichment analysis revealed that cancer-related pathways including epithelial-to-mesenchymal transition, focal adhesion, and transforming growth factor-β (TGF-β) signaling pathways were enriched in high ANTXR1 expression tumors." (PMID 33385012, 2020). "The protein Anthrax Toxin Receptor 1 (ANTXR1) has been identified as a potential receptor for SVA and shown to interact with the virus capsid during infection of human H446 cancer cells, however, the contribution of this molecule to SVA infection in swine await experimental confirmation." (PMID 31849928, 2019). "This figure shows that, paradoxically, a higher immune score (more infiltration of immune cells) is correlated to higher levels of ANTXR1, suggesting that for some cancers the infiltration of immune cells may not be a definitive factor when treating cancer." (PMID 39917181, 2024).
infection (12 papers, 2011 to 2022). The state of being infected such as from the introduction of a foreign agent such as serum, vaccine, antigenic substance or organism. "In the present study, cells from an ANTXR1 KO pig that were confirmed to have two KO alleles showed resistance to infection with SVA-EGFP." (PMID 35322150, 2022). "Gene edited ANTXR1 null pigs were created to investigate the role of ANTXR1 in SVA infection both by both in vitro and in vivo challenges." (PMID 35755158, 2022). "ANTXR1 participates in a variety of seemingly unrelated activities, including the host response to infection with Bacillus anthracis, the regulation of collagen deposition in tissues, and as a receptor for SVA." (PMID 35322150, 2022). "The reporter SVA was used to study the role of pig ANTXR1 (pANTXR1) in SVA infection in a porcine alveolar macrophage cell line (PAM-Tang cells)." (PMID 35498725, 2022). "A combination of co-immunoprecipitation assays and cellular infection experiments showed the necessity of ANTXR1 glycosylation for successful SVV attachment and cellular entry." (PMID 33924774, 2021). "In this study, we characterized the glycosylation of recombinant ANTXR1 extracellular domain fused to a fragment-crystallizable (Fc) region and its importance in SVV-ANTXR1 interactions and cellular infection." (PMID 33924774, 2021). "Thus, the negative responses by KO pig 53 to SVA in vivo and the resistance of KO fibroblasts from Pig 52 with a confirmed genotype to SVA infection in vitro were instrumental in verifying that ANTXR1 is the receptor for SVA in pigs." (PMID 35322150, 2022). "Similar results were obtained for the ANTXR1 KO pigs after infection with SVA." (PMID 35322150, 2022). "In order to assess if N-glycosylation on ANTXR1 is necessary for successful viral attachment and entry, we performed infection studies with GFP-tagged virus (SVV-GFP) and ANTXR1-Fc protein that was pre-incubated in the presence or absence of PNGase F." (PMID 33924774, 2021).
blood disorders (1 paper, 2022). "Our study also showed that ANTXR1 may regulate the proliferation and differentiation of hematopoietic cells, though the Wnt/β-catenin pathway, which may help to establish a possible therapeutic target for the treatment of blood disorders." (PMID 36065334, 2022).
heart disease (1 paper, 2025). "The prominent gene expression alterations in CFs following T8Ab treatment suggest that Antxr1-positive CFs are the principal effectors of ANTXR1 activity in cardiac disease." (PMID 41039173, 2025). "Together, these data demonstrate widespread induction of ANTXR1 in human heart disease." (PMID 41039173, 2025). "Given its regulation by ischemia and involvement in collagen uptake, we postulated that ANTXR1 may minimize heart disease by restraining excessive fibrosis after MI." (PMID 41039173, 2025).
ANTXR1 also shares sentences with these, for which no sentence is quoted: breast tumor (6 papers); hemangioma (5); lung cancer (5); neuroblastoma (4); lung adenocarcinoma (3); ovarian carcinoma (3); genetic diseases (2); infantile hemangioma (2); invasive breast carcinoma (2); osteoarthritis (2); angiosarcoma (1); benign prostatic hyperplasia (1); bone metastasis (1); cervical cancer (1); cervical squamous cell carcinoma (1); colorectal adenocarcinoma (1); endometrial cancer (1); esophageal carcinoma (1); fibrous dysplasia (1); growth deficiency (1); head and neck squamous cell carcinoma (1); hematopoietic neoplasm (1); kidney tumors (1); liver cancer (1); metastatic colorectal cancer (1); metastatic disease (1); nasopharyngeal tumors (1); non-small cell lung carcinoma (1); osteofibrous dysplasia (1); osteoma (1).
A further 5 diseases each share a sentence with ANTXR1 in 1 paper.